BDNF (brain derived neurotrophic factor)
Diseases named in the same sentence as BDNF in open-access papers (continued):
Sharing a sentence is not in itself a finding about the gene and the disease.
nicotine dependence (continued). "Our novel findings of dysregulated methylation patterns in exon IV of the BDNF gene further support the hypothesis that epigenetic regulation of BDNF plays a role in nicotine dependence in a gender-dependent manner." (PMID 35836661, 2022). "However, to the best of our knowledge, no studies have investigated the epigenetic regulation of the BDNF gene in the context of nicotine dependence and smoking cessation." (PMID 35836661, 2022). "Given the established association between smoking and cognitive performance and the important role of BDNF in cognition and in nicotine dependence, it would be of interest to explore the relationships between smoking, cognitive performance and BDNF in a healthy population." (PMID 30659208, 2019). "Taken together, these findings suggest that smoking may affect the peripheral BDNF levels, and BDNF system may be involved in the etiology of nicotine dependence." (PMID 30659208, 2019). "While our study did not reveal an association between the investigated brain-derived neurotrophic factor polymorphisms (rs6265, rs10767664 and rs2030323) and nicotine use, it is essential to acknowledge that nicotine dependence is a complex, multifactorial phenotype." (PMID 40806241, 2025). "Furthermore, BDNF could be involved in the steps of a cascade of several dysregulated pathways involved in nicotine dependence." (PMID 35836661, 2022). "This study investigated whether a gene polymorphism causing a Val66Met substitution (rs6265) in brain-derived neurotrophic factor (BDNF) is associated with smoking initiation, smoking cessation, nicotine dependence and age of smoking initiation, in Japanese participants." (PMID 30815604, 2019). "Animal studies of nicotine dependence have shown the longer effect of direct current stimulation affecting LTP and that this effect was dependent on N-methyl D-aspartate and brain-derived neurotrophic factor (BDNF)." (PMID 36480510, 2022). "In addition, our findings of the significant association between BDNF levels and CO concentrations and the trend toward significant association between BDNF and FTND total score seem to support this hypothesis that greater nicotine dependence or smoking severity elevates BDNF in smokers." (PMID 30659208, 2019). "Consequently, these results indicate that BDNF Val66Met has an effect on nicotine dependence, but this effect is not interactive with 5-HTTLPR polymorphism." (PMID 30815604, 2019). "In summary, levels of BDNF and cortisol measured at 10:00 pm appear to be dependent on cigarette smoking and could represent the relationship between the mesolimbic system and the HPA axis in the mechanism of nicotine addiction." (PMID 29069228, 2017).
alcohol addiction (14 papers, 2012 to 2025). "BDNF has been implicated in the development of alcohol addiction due to its role in the regulation of synaptic plasticity in the Hip and NAc." (PMID 29896126, 2018). "Reduced brain-derived neurotrophic factor (BDNF) expression has been associated with AUD and alcohol addiction, however the effects of activation of BDNF signalling in the brain on voluntary alcohol intake reinstatement and relapse are unknown." (PMID 32369970, 2020). "Future studies are necessary to further evaluate the role of specific HDAC and DNMT variants that are involved in the epigenetic regulation of BDNF or other genes associated with synaptic plasticity during the development of pathological behaviors associated with stress and alcohol addiction." (PMID 23584115, 2012). "As a neurotrophic factor, the BDNF regulates a variety of neuronal processes and implicates the development of alcohol addiction." (PMID 37962470, 2023). "The previous literature on neurotrophic factors and their role in alcohol addiction highlights an upregulation of BDNF mRNA and protein expression in response to prolonged alcohol intake, followed by a gradual decrease in expression." (PMID 32369970, 2020). "Concentration of pro-BDNF and p75NTR proteins was increased, while concentration of TrkB reduced in subjects with alcohol addiction in comparison to healthy controls." (PMID 32231011, 2020). "Considering the key role of BDNF in alcohol addiction and VTA involvement in reward processing, we studied the expression of BDNF in the VTA when alcohol consumption behavior was evident in these two ethanol consumption patterns." (PMID 32508571, 2020). "Increased BDNF levels during abstinence have been observed in alcohol addiction, although some aspects may differ between studies." (PMID 34060728, 2022). "The overall scenario suggests that BDNF could be a candidate biomarker of severity and prognosis in alcohol addiction." (PMID 34060728, 2022). "An increasing number of literatures suggest a role of BDNF in alcohol addiction." (PMID 32508571, 2020). "Latest research highlights the importance not only of gene expression itself but also of epigenetic regulation of genes encoding for neurotrophic factors, including nerve growth factor (NGF) and brain-derived neurotrophic factor (BDNF), in alcohol addiction." (PMID 36834747, 2023). "The current data extend our understanding of the different patterns of neuroadaptation, specifically of BDNF and NGF, within two key brain regions (hippocampus and frontal cortex) in an animal model of late-stage sustained alcohol addiction." (PMID 26930631, 2016). "In this study, we investigated correlations between serum BDNF and NT3 with alcohol in breath at admission as well as body-mass-index, lipoprotein profile and lifestyle factors in 110 male in-patients diagnosed with alcohol addiction on the first day after admission and at discharge." (PMID 25408911, 2013).
intracerebral hemorrhage (14 papers, 2016 to 2025). A cerebrovascular disorder characterized by bleeding into one or both cerebral hemispheres including the basal ganglia and the cerebral cortex. "In this study, intraventricular administration of BDNF in rats showed improved functional outcomes following intracerebral hemorrhage." (PMID 40895108, 2025). "The local simultaneous administration of BDNF and uPA provided effective neuroprotection of brain tissue after intracerebral hemorrhage, promoted survival of experimental animals and their neurological recovery, and decreased lesion volume." (PMID 35740368, 2022). "uPA had effect similar to BDNF: it stimulated the survival of rats (86% at 10 days after intracerebral hemorrhage)." (PMID 35740368, 2022). "We studied the protective and pro-regenerative properties of BDNF and its combination with uPA in a rat model of intracerebral hemorrhage." (PMID 35740368, 2022). "Using a model of intracerebral hemorrhage in rats, we investigated the neurotrophic and neuroprotective effect of BDNF combined with uPA." (PMID 35740368, 2022). "Previous studies have already shown that transplantation of F3.BDNF cells can be beneficial for behavioral recovery in ICH (intracerebral hemorrhage) and MCAo (middle cerebral artery occlusion) models." (PMID 34203489, 2021). "F3.BDNF cells have been reported that they can lead to functional recovery and neuroprotection in an animal model of intracerebral hemorrhage." (PMID 34203489, 2021). "We believe that this can be explained by the severity of the condition (intracerebral hemorrhage) and the insufficiency of action of a single molecule (BDNF), even though it has a strong proven neuroprotective effect." (PMID 34959314, 2021). "In an intracerebral hemorrhage mouse model, intracranial implantation of BDNF-overexpressing 3T3 fibroblasts significantly promoted poststroke neurogenesis and functional recovery." (PMID 32399020, 2020). "This relation becomes more pronounced in individuals with haemorrhagic stroke, as found in a study where the BDNF level of those with intracerebral haemorrhage (ICH) score of 1 was 14.1 ± 3.7 ng/ml, while that of those with ICH score of 3 and above was 5.3 ± 2.3 ng/ml." (PMID 38707431, 2024). "We have shown that the optimal therapeutic effect is observed when using the MSC secretome 5- or 10-fold concentrated (with the BDNF content of 15 ng/mL and 30 ng/mL, respectively) being administered intravenously into the tail vein of rats one hour after the modeling of intracerebral hemorrhage." (PMID 37376058, 2023). "Such outstanding pro-regenerative properties of BDNF and uPA could be applied for treating currently untreatable severe neurological conditions, such as intracerebral hemorrhage." (PMID 35740368, 2022). "Therefore, in the present study we explored the potential of a combination of human BDNF and uPA to stimulate brain tissue recovery after intracerebral hemorrhage." (PMID 35740368, 2022). "However, complementing BDNF with uPA significantly increased the survival of experimental animals after intracerebral hemorrhage and reduced the severity of the observed neurological deficits." (PMID 35740368, 2022). "Prolonged expression of these proteins may contribute to brain injury and dysfunction; however, in the model of intracerebral hemorrhage, a pulse injection of BDNF and uPA and subsequent activation of microglia/monocytes/macrophages was beneficial." (PMID 35740368, 2022). "Similarly, dexmedetomidine pretreatment before intracerebral hemorrhage ameliorates the resulting impairment of short-term and spatial learning memory by suppressing apoptosis and enhancing BDNF expression." (PMID 27768775, 2016). "Brain-derived neurotrophic factor (BDNF) is a pivotal growth factor for neuronal survival; however, its precise role following intracerebral hemorrhage (ICH) remains poorly understood." (PMID 40895108, 2025).
intracerebral hemorrhage (continued). "The addition of the MSC-B group to the experiment was due to the expectation of an additive therapeutic effect of the BDNF protein (immediate) and MSC microvesicles (delayed effect) during the long brain recovery process after the intracerebral hemorrhage." (PMID 34959314, 2021). "In addition, the significant involvement of sensitive P2X4R in mediating increased BDNF and p38-MAPK for intracerebral hemorrhage and pain hypersensitivity has been reported." (PMID 35821455, 2023). "Similarly, fusing BDNF with a collagen-binding domain successfully retained BDNF for a longer time from degradation and promoted neurogenesis in the SVZ in an intracerebral hemorrhage model." (PMID 32399020, 2020).
Pain (14 papers, 2013 to 2025). An unpleasant sensory and emotional experience associated with actual or potential tissue damage, or described in terms of such damage. "To determine whether microglia-derived BDNF is critical for synaptic plasticity associated with chronic neuropathic pain in male mice, we examined the dynamics of postsynaptic dendritic spines in the S1 with transcranial two-photon microscopy." (PMID 34292944, 2021). "Research from several groups has revealed an important role of both pro- and anti-inflammatory cytokines and brain-derived neurotrophic factor (BDNF) in neuropathic and other chronic pain states." (PMID 35454990, 2022). "In conclusion, the current study suggests that decreased BDNF-TrkB signaling in the mPFC plays key roles in individual differences of the anhedonia-like phenotype in rats with neuropathic pain." (PMID 29882089, 2020). "Affirming a role for augmented spinal BDNF-TrkB signalling in the pathobiology of neuropathic pain were observations that repeated i.t. administration of anti-BDNF or a BDNF-sequestering TrkB-Fc chimera protein, abolished neuropathic pain behaviours." (PMID 26065639, 2015). "MiR124 is an especially important candidate, as it is involved in the regulation of both BDNF and IGF-1, is sensitive to uncontrollable intermittent tailshock, and has been shown to inhibit nociceptive behavior associated with neuropathic pain." (PMID 25278846, 2014). "Moreover, studies in other models of neuropathic pain have demonstrated BDNF's ability to reverse chronic pain signals in the spinal dorsal horn, besides emerging evidence points to its anti-inflammatory effects on microglia, further supporting its role in pain resolution." (PMID 40329125, 2025). "Furthermore, BDNF‐TrkB signaling also appears important for the development of inflammatory and neuropathic pain conditions, so targeting this pathway may provide a dual role by acting as an opioid adjuvant to reduce OIH and improving the chronic pain condition itself." (PMID 34096178, 2021). "The authors reported hotplate hypersensitivity and formalin hyposensitivity in female mice after developmental BDNF deletion and no change in mechanical thresholds in a nerve injury induced model of neuropathic pain." (PMID 30627644, 2018). "Thus, in our model of neuropathic pain, TNF-α, IL-1β, IL-6 and BDNF release from the spinal cord was investigated to ascertain, for the first time, whether FPR agonists might affect nociception by modifying the levels of inflammatory cytokines and BDNF in the spinal cord." (PMID 35454990, 2022).
type 1 diabetes (14 papers, 2013 to 2025). "Lower BDNF levels have also been linked with poorer neurocognitive function in children with type I diabetes." (PMID 35127775, 2021). "In the present study, we investigated the effects of BDNF overexpression on reducing neuroinflammation and the underlying mechanism in mice with type 1 diabetes induced by streptozotocin (STZ)." (PMID 31165005, 2019). "Previous studies have reported that BDNF inhibits hippocampus inflammation in type 1 diabetic mice via the inactivation of the RAGE–NF-κB pathway." (PMID 36496991, 2022). "According to a report, BDNF is inhibited in the hippocampus of type-1 diabetes mice, after NF-κB was activated." (PMID 35406030, 2022). "Another study showed that BDNF microinjection into the hippocampus significantly decreased neuroinflammation in a type 1 diabetes mouse model." (PMID 34822458, 2021). "In summary, there is a need for further studies about the role of BDNF level in serum among patients with type 1 diabetes." (PMID 32012942, 2020). "It was proved that physical exercise increases the secretion of BDNF into the serum in people with type 1 diabetes." (PMID 32012942, 2020). "There are only few data about BDNF and type 1 diabetes, mainly experimental data." (PMID 32012942, 2020). "Regarding high-intensity exercise or combined exercise, a previous study in 10 inactive individuals with type 1 diabetes showed that acute HIIT protocols result in larger increases in serum BDNF concentrations than acute low- or moderate-intensity exercise protocols." (PMID 29997519, 2018). "The secondary endpoint of the research was to analyze the impact of maternal age, duration of type-1 diabetes mellitus, BMI, HbA1c, TSH, leptin, and BDNF on neonatal overweight." (PMID 36771307, 2023).
bulimia nervosa (13 papers, 2017 to 2024). A disorder characterized by recurrent episodes of binge-eating over which the individual feels a lack of control; these episodes of binge-eating are followed by recurrent compensatory behavior to prevent weight gain, usually self-induced vomiting. "They reported that bulimia nervosa was associated per se with an hypermethylation within BDNF promoter region sites." (PMID 28619017, 2017). "Interestingly, increased BDNF plasma levels have been previously associated with decreased reward learning in patients with bulimia nervosa." (PMID 34325733, 2021). "More recently, Thaler and collaborators analyzed DNA methylation patterns in the promoter region of BDNF gene in women with bulimia nervosa and with history of BPD and/or trauma events." (PMID 28619017, 2017).
Aphasia (12 papers, 2019 to 2025). An acquired language impairment of some or all of the abilities to produce or comprehend speech and to read or write. "Recent reviews have concurred that only four prior studies have directly examined the effect of any genetic variant on aphasia recovery, and all four have examined BDNF rs6265." (PMID 40658687, 2025). "Individuals with the atypical variant of BDNF (i.e., -met allele carriers) show less ability to benefit from cortical plasticity induced by tDCS and aphasia therapy." (PMID 40808812, 2025). "The article suggests that typical BDNF is linked to lower aphasia severity and higher accuracy in semantic memory and language abilities compared to atypical BDNF." (PMID 40492169, 2025). "In individuals living with post-stroke aphasia, BDNF polymorphism has been linked to aphasia severity and stimulation-induced neuroplasticity." (PMID 40919410, 2025). "The atypical BDNF genotype (Met allele carriers) is more severe than the typical BDNF genotype (Val/Val) after aphasia." (PMID 37091130, 2023). "These limitations justify future studies to explore the association between BDNF polymorphism and poststroke aphasia especially considering the emergence of neuromodulation therapy that promotes language improvement." (PMID 34367374, 2021). "Firstly, there are a relatively limited number of original articles on the topic of BDNF polymorphism and poststroke aphasia-related outcomes, most prominently in the scope of BDNF genotypes." (PMID 34367374, 2021). "The findings from this preliminary study suggested that there is insufficient evidence to conclude that BDNF polymorphism plays a role in poststroke aphasia recovery." (PMID 34367374, 2021). "This review assesses the recent evidence on the association between the BDNF polymorphism and aphasia recovery in poststroke patients." (PMID 34367374, 2021). "Based on these findings, the Val66Met polymorphism of BDNF is linked with more severe aphasia at baseline, poorer improvement in language improvement with time, and reduced cortical activation." (PMID 34367374, 2021). "Based on the findings of the selected articles, it seems that a correlation between BDNF polymorphism and aphasia recovery exists, although the exact mechanisms underpinning this effect are still unclear." (PMID 34367374, 2021). "Carriers of the Val66Met polymorphism of BDNF gave a poorer response to aphasia intervention and presented with more severe aphasia." (PMID 34367374, 2021). "One of the studies demonstrated insufficient evidence to conclude that BDNF polymorphism plays a role in poststroke aphasia recovery." (PMID 34367374, 2021). "The main impetus of the present review is to investigate whether BDNF Val66Met polymorphism is associated with language function in people with poststroke aphasia." (PMID 34367374, 2021). "In conclusion, some evidence suggests that polymorphism in the BDNF gene may modulate language recovery in poststroke aphasia." (PMID 34367374, 2021). "Still, the role of BDNF polymorphism in poststroke aphasia is relatively unclear." (PMID 34367374, 2021). "Hence, the diversity of BDNF polymorphism among worldwide populations would provide important implications for the implementation of further studies on poststroke aphasia." (PMID 34367374, 2021). "In an RCT involving tDCS and language therapy in individuals living with post-stroke aphasia, BDNF val/val carriers showed greater benefit from a-tDCS and aphasia therapy than val/met carriers." (PMID 40919410, 2025). "The studies of BDNF in aphasia also differ in other methodological ways that make it difficult to draw clear comparison." (PMID 40658687, 2025). "Aim 1: Does Val/Val BDNF status have an effect on the probability of good chronic naming performance in people with aphasia?" (PMID 40658687, 2025).